RNU5B-4P (RNA, U5B small nuclear 4, pseudogene)
Gene: Small nuclear RNA gene on chromosome 5 (139,447,907 to 139,448,017, forward strand). Ensembl gene ENSG00000200378.
Homologues: Orthologues: chimpanzee U5 (100% identical), macaque U5 (93% identical). Paralogues in human: RNU5A-7P (83% identical), RNU5E-4P (83% identical), RNU5A-3P (82% identical), RNU5E-7P (82% identical), RNU5E-5P (79% identical), RNU5E-6P (79% identical), RNU5A-4P (78% identical), RNU5F-3P (78% identical), RNU5E-8P (77% identical), RNU5E-10P (77% identical), RNU5F-7P (77% identical), RNU5A-6P (76% identical), and 13 more.